IL2 (interleukin 2)
Diseases named in the same sentence as IL2 in open-access papers (continued):
Sharing a sentence is not in itself a finding about the gene and the disease.
COVID-19 (continued). "We found that the lung CTs of patients with moderate or severe pneumonia due to COVID-19 were more likely to have GGO if they had increased levels of IL-2, IL-4, and INF-γ, and that IL-2 was significantly and independently associated with GGO." (PMID 33967617, 2021). "These included many inflammatory signaling pathways such as IFN- II, CCL, CXCL, IL1, and IL2, suggesting that moderate and critical COVID-19 strongly trigger a series of inflammatory responses." (PMID 34858473, 2021). "Cytokine profiles in COVID-19 patients have revealed increased levels of interleukin-1β (IL-1β), IL-2, IL-6 and tumor necrosis factor-alpha (TNFα)." (PMID 33927728, 2021). "COVID-19 patients showed a profile of pro-inflammatory serum cytokines compared to controls, with higher levels of IL-2, IL-6, IL-15, and IP-10." (PMID 33718270, 2021). "In COVID-19 patients, the cytokine IL2 or its receptors (IL2R) elevated and increased the condition's severity." (PMID 33907373, 2021). "Severely ill patients hospitalised with COVID-19 exhibit increased levels of Interleukin (IL)-1β, IL-2, IL-6, IL-7, IL-8, IL-10, IL-17, granulocyte colony stimulating factor (G-CSF), monocyte chemoattractant protein 1 (MCP-1) and tumor necrosis factor (TNF)." (PMID 34205262, 2021). "In COVID-19 (+) patients, concentrations of both IL-2 and sIL-2R are higher than in COVID-19 (−) patients, especially in severe patients." (PMID 34575258, 2021). "Our in silico results have evidenced affinity between mullein phytochemicals (Flavones and O-metilated flavones) and pro-inflammatory cytokines (IL-2 and TNF-α), molecules implicated in inflammatory processes related to the respiratory system and COVID-19." (PMID 34356473, 2021). "Based on our results, a higher IL-2/INFγ ratio was a strong predictor of a critical course of COVID-19, and was significantly increased in COVID-19 patients who died." (PMID 34071149, 2021). "CRP was positively associated with IFNγ, IL-2, TNFα IL-1α IFNβ IL-6 IL-17A IL-10, CXCL-10 and VEGF in children with PIMS-TS and COVID-19." (PMID 33813138, 2021). "While cytokine storm underlies the severe symptoms of COVID-19, interleukin 7 (IL-7) and IL-2 increase in plasma of COVID-19 patients, and IL-7 and IL-2 reduce the expression of ACE2 in mice." (PMID 33799583, 2021). "Regarding COVID-19, it has been suggested that circulating sIL-2Rα contributes to the lymphopenia through inhibiting IL-2 signaling." (PMID 33584733, 2021). "COVID-19-related CRS patients exhibited increased plasma levels of IL-2, IL-7, IL-10, G-SCF, MCP-1, MIP-1α, and TNF-α." (PMID 34884813, 2021). "Cytokine excess, in particular IL-2, IL-4, IL-6, TNF-α, and IFN-Ɣ are known drivers of the overactive inflammatory response and associated COVID-19 severity." (PMID 34675810, 2021). "Those ICU admitted COVID-19 patients exhibited increased plasma levels of IL-2, IL-7, IL-10, granulocyte colony-stimulating factor, monocyte chemoattractant protein- 1, interferon-inducible protein 10, and TNF-α than the non-ICU admitted patients." (PMID 33869282, 2021). "Cytokine profiles observed in COVID-19 patients have revealed increased levels of IL-1β, IL-2, IL-6, and TNF-α and increased NF-κB pathway activity." (PMID 33927728, 2021). "Patients with severe COVID-19 have higher serum concentration of IL-6, IL-10, IL-2 and IFN-γ, higher numbers of neutrophils in the peripheral blood and reduced counts of T cells (particularly CD8+ T cells) compared with patients with mild disease." (PMID 33906375, 2021). "In severely sick COVID-19 patients, cytokine storm syndrome was examined, and it was reported that the extent of interleukins (IL-2, IL-7, IL-10) was high in fundamentally sick patients." (PMID 33907373, 2021). "A recent study demonstrated that COVID-19 severe patients had a low level of counts of T cells and a high level of IL-2, IL-6, IFN-γ, and IL-10 compared with the mild patients, similar to the results in SARS and MERS." (PMID 33833618, 2021).
COVID-19 (continued). "Many cytokines in COVID-19 patients were significantly different from those in healthy individuals, including IL-2, IL-4, IL-6, CCL2, IFN-γ, and TNF-α." (PMID 34489974, 2021). "First, we compared the prevalence, magnitude, and phenotypical profile of SARS-CoV-2–responding CD4+ T cells (e.g., cells producing IFN-γ, TNF-α, or IL-2) between hospitalized non–COVID-19 controls and confirmed COVID-19 patients." (PMID 33945513, 2021). "According to a recent report analyzing 138 hospitalized patients with COVID-19 high plasma concentrations of cytokines and chemokines including IL-2, IL-7, IL-10, G-CSF, IP-10, MCP-1, MIP-1A, and TNF-α were observed in the COVID-19 severe cases." (PMID 33154753, 2020). "We first compared the levels of IFN-γ, TNF-α, IL-2, IL-4, IL-6 and IL-10 in serum samples from control group and COVID-19 patients." (PMID 32475230, 2020). "A study indicated that COVID-19 patients treated in the intensive care unit with severe clinical features had a high level of innate cytokines IL-2, IL-10, IL-7, TNF-α, chemokines IP-10, MCP-1, and MIP-1A." (PMID 33101440, 2020). "We therefore examined the concentrations of serum cytokines, including TNF-α, IFN-γ, IL-2, IL-4, IL-6, and IL-10, from these COVID-19 patients to explore the influence of cytokine signaling." (PMID 32425950, 2020). "Most patients with severe COVID-19 show significantly elevated serum levels of inflammatory cytokines, such as IL-6 and IL-1, as well as IL-2, IL-17, G-GSF, GM-GSF, IP-10, MCP1, MIP-1a (also known as CCL3), and TNF, known as a cytokine storm." (PMID 32983180, 2020). "As cytokine storms played a critical role in the deterioration of COVID-19, we also detected the Th1/Th2 cytokines including IL-2, IL-4, IL-6, IL-10, TNF-α, and IFN-γ in patients infected with COVID-19." (PMID 33061829, 2020). "Higher plasma levels of cytokines, including interleukin (IL)-6, IL-2, IL-7, IL-10, and tumor necrosis factor-α, were found in patients with COVID-19, which implies the occurrence of a cytokine storm and its association with disease severity." (PMID 33335906, 2020). "Intriguingly, severe COVID-19 patients show elevated serum IL-2 and soluble CD25 (IL-2 receptor α chain)." (PMID 33178221, 2020). "Individually, laboratory abnormalities have been reported in COVID-19 patients, including an elevation of inflammatory markers and liver enzymes, abnormal renal function tests, and an elevated serum soluble interleukin 2 (IL-2) receptor (sIL2R) and IL-6." (PMID 32957548, 2020). "Our results also demonstrated that severe COVID-19 patients had higher concentrations of IL-6, IL-8, IL-2,TNF-α, and IFN-γ in the serum than mild case patients, which suggested that the magnitude of cytokine storm was associated with the disease severity." (PMID 32484453, 2020). "For instance, in plasma of COVID-19 patients, high concentrations of IL-2, IL-6, and IL-7 were observed." (PMID 33206688, 2020). "Severe hospitalized COVID-19 patients overexpressed pro-inflammatory cytokines (i.e., IL-1 beta, IL-2, IL-6, IL-17, TNFα)." (PMID 33019628, 2020). "The underlying pathophysiology of COVID-19 involves a maladaptive immune response to SARS-CoV-2 infection with increased levels of IL-6, IL-10, IL-2 and TNFα produced by macrophages, and fewer CD4+ and CD8+ T cells, but no significant changes in B-cell counts." (PMID 32399655, 2020). "When comparing COVID-19 ARDS patients with HC, stimulation of PBMC by the overlapping S peptide pool led to a strong significant production of the Th1 or effector cytokines IFN-γ, TNF-α and IL-2 in COVID-19 ARDS patients." (PMID 32591408, 2020). "Higher percentages of CD4+ T cells producing IFNγ, TNFα, IL-2, and IL-17A and CD8+ T cells producing IL-2 and IL-17A have been detected by flow cytometry in PBMCs from COVID-19 patients vs. healthy controls after in vitro stimulation." (PMID 33634100, 2020).
COVID-19 (continued). "Hospitalized patients with severe COVID-19 show high levels of IL-2, IL-7, IL-10, G-CSF, TNF, CXCL10, MCP1, and MIP1α in serum, suggesting that severe COVID-19 is dictated as a cytokine release syndrome (CRS), which is a disorder induced by cytokine storms." (PMID 33014208, 2020). "However, the levels of TNF-α and IL-2 were higher in the breastfeeding mothers with COVID-19 than in the vaccinated breastfeeding mothers or in the control group but still within the reference range." (PMID 40141241, 2025). "Importantly, our results identify immunological biomarkers beyond IFN-γ, particularly IL-2, as additional tools to assess the cell-mediated immune response to COVID-19 vaccination." (PMID 41246331, 2025). "Also, the double mutant alleles (AA) of rs4646116 were responsible for increased expression level of IL-2 in TB-COVID-19 patients." (PMID 40196114, 2025). "In addition, the levels of IFN-γ and IL-2 in patients with acute COVID-19 (≥55 years old) are low, and the activation of T cells derived from dendritic cells is impaired, which will also lead to a reduced adaptive immune response." (PMID 40230855, 2025). "Escalating concentrations of recombinant spike can activate human lung macrophages, triggering the production of proinflammatory cytokines that mirror the “cytokine storm” signature observed in clinical COVID-19 cases (IL-2, IL-4, IL-6, IL-1β, IL-8, IFN-γ, TNF-α, and CXCL10)." (PMID 41012643, 2025). "High levels of IL-2 were detected in the epitopes obtained through our multidimensional exploration in the ELISpot experiment, revealing the preferred epitope response of COVID-19 NP-specific CD8+ T cells." (PMID 39591116, 2024). "Additionally, SARS-CoV-2 infection can activate NF-κB, resulting in a "cytokine storm" that releases plenty of inflammatory factors, including IL-2, which in turn leads to lung damage in COVID-19 patients." (PMID 38967887, 2024). "Together, these data suggest that IL-2 released by T cells activated by DCs stimulated with spike protein may serve as an amplifier in inducing CRS in patients with COVID-19 in a manner of cooperation with spike protein." (PMID 39359733, 2024). "This study shows albumin, lymphocytes, platelets and ferritin as factors that may correlate with the severity of COVID-19, and with regard to pro-inflammatory cytokines, the authors found IL-6, IL-10, IL-2 and IL-17 to be elevated in severe patients." (PMID 38807995, 2024). "Interestingly, the genetic variant chrX:15,584,534_ of the ACE2 gene correlated positively with CD40L, IL-1β, IL-2, IL-15, and IL-17A in COVID-19 patients." (PMID 38855114, 2024). "Many patients with severe COVID-19 exhibit a noticeable elevation of IL-2 in their plasma." (PMID 39359733, 2024). "Similarly, a study conducted on patients with severe COVID-19 revealed that the levels of IL-2, IL-6, IL-10, and TNF-α were significantly higher compared to non-severe patients." (PMID 38355623, 2024). "Interestingly, several cytokines such as IFN-γ, IFN-α, IL-1β, IL-2, IL-12p70, IL-17A and IL-33) decreased in moderate and severe COVID-19 patients compared to mild cases or healthy controls." (PMID 38855114, 2024). "Out of the 17 cytokines tested, nine (IL-1β, IL-2, IL-4, IL-5, IL-12, IL-13, IL-17, granulocyte colony-stimulating factor (G-CSF), granulocyte-macrophage colony-stimulating factor (GM-CSF)) were undetectable in the peripheral blood of COVID-19 patients." (PMID 39408857, 2024). "Elevated levels of other inflammatory cytokines and chemokines like IL-2 and IL-8, with increased levels of eosinophil and neutrophils, might provoke immune abnormality in patients affected with COVID-19." (PMID 38255322, 2024). "Herein, we tested whether immunomodulation focusing on interleukin (IL)-6, IL-17, and IL-2, could improve the clinical outcomes of patients admitted with COVID-19." (PMID 37075454, 2023).
COVID-19 (continued). "Moreover, the importance of high IL-2 levels, which indirectly stimulate B cells via TH-cell differentiation, was also evidenced in vaccinated or COVID-19 as well as in SARS-CoV-1 convalescent individuals." (PMID 36259394, 2023). "Patients with severe COVID-19 had reduced lymphocyte numbers and frequency levels; greater naive cells (Tregs); lower frequencies of central memory, effector memory, and stem cell memory, and higher plasma levels of IL2, IL7, IL15, and IL21." (PMID 36992283, 2023). "By lowering the bioavailability of IL-2 to Treg cells, soluble IL-2 receptors may limit the development of Treg cells in COVID-19 patients." (PMID 36992283, 2023). "Also, numerous studies have shown that COVID-19 patients have increased levels of IL-1β, IL-2, IL-6, IL-10, TNFα, IFNγ, and that these cytokines correlate with the severity of the disease." (PMID 36835858, 2023). "Although not statically significant, the polar charts show a signal towards the reduction in the production of pro-inflammatory cytokines, and specifically IL-1β, IL-2, IL-12, IL-13, IL-17A secreted by M2 macrophages of COVID-19 patients, after PD1 stimulation." (PMID 37153620, 2023). "Hence, administering modest amounts of recombinant IL-2 to severely infected patients with COVID-19 should alleviate lymphopenia and restore the natural T-cell numbers." (PMID 36679947, 2023). "Also, acute COVID-19 children had significantly elevated levels of cytokines, IFNγ, IL-2, TNFα, IFNβ, IL-6, IL-12, IL-17A and Granulocyte-Colony Stimulating Factors G-CSF in comparison to control children." (PMID 37013538, 2023). "Elevated IL-2 levels observed in individuals with COVID-19 could potentially suggest the activation of T cells." (PMID 38106427, 2023). "The findings suggest that the expression levels of SDF-1, MBL, and IL-2 could be useful biomarkers for stratifying COVID-19 patients into different subtypes." (PMID 37949890, 2023). "The induction of these transcriptional alterations was particularly pronounced for the first 1–2 weeks after the onset of symptoms and is consistent with the lower IL2-AIS score observed among community COVID-19 patients sampled later, during the recovery phase." (PMID 37700317, 2023). "We found that most IL2-AIS genes were regulated in the opposite direction in COVID-19 patients." (PMID 37700317, 2023). "Furthermore, in a sample of 317 patients diagnosed with COVID-19, high serum levels of IL-17 and IL-2 and low levels of IL-4 and IL-10 appeared to constitute a cytokine profile of long COVID-19." (PMID 36992491, 2023). "Except for IgG 1/IgG 4, LY #, and HGB, the severe COVID-19 group exhibited significantly elevated levels of IL-2, IL-6, IgG 2/IgG 1, IgG Sum/IgG 1, IgG 2/IgG Sum, CRP, PT, INR, DD, WBC, NE #, NLR, RDW, and PDW in comparison to the non-severe COVID-19 group (p<0.05)." (PMID 38106427, 2023). "Similarly, a recent study has reported that severe COVID-19 was related to elevated levels of IL-2 induced through IL-2R-JAK-STAT5 signalling pathways." (PMID 37569646, 2023). "The mediators CCL3, CCL4, CCL2, CCL5, IL-12, IL-15, IL-1Ra, and PDGF were higher in healthy volunteers, while the mediators CCL11, CXCL10, IL-1b, IL-6, TNF-a, IFN-g, IL-17, IL-9, IL-10, IL-13, FGF-basic, G-CSF, GM-CSF, IL-7, and IL-2 were increased in COVID-19 positive patients." (PMID 37903875, 2023). "A corollary of our results is that low-dose IL-2 immunotherapy could have a therapeutic application to revert this prolonged period of immune dysfunction in recovered COVID-19 patients and reduce the occurrence of PASC." (PMID 37700317, 2023). "As a result, it can be noted that targeting IL-2 could effectively prevent fatal outcomes of the disease and increase the quality of life of patients with COVID-19." (PMID 37649897, 2023).
COVID-19 (continued). "Additional studies have also revealed that patients with severe COVID-19 have a significantly elevated cytokine profile of IL-2, IL-6, IL-7, IL-10, IP-10, MCP-1, TNF-α, macrophage inflammatory protein 1 alpha, and granulocyte-CSF compared to patients with mild to moderate COVID-19." (PMID 37457959, 2023). "Consequently, patients with severe COVID-19 have considerably higher blood levels of IL-2, IL-6, TNF-α, IL-1, IL-10, IFN-γ, IL-8/CXCL8, and CXCL10/IP-10 during the cytokine storm, potentially because of NF-κB via selective activation." (PMID 36851766, 2023). "In this work we found elevated proinflammatory cytokines IL-6, IL-10, IL-2 and IL-17, and importantly we noted that 12 of 20 COVID-19 severely ill patients and 13 of 20 critically ill patients had lymphopenia (lymphocyte values below 1000/ mL), which coincides with the observations of other authors." (PMID 36835858, 2023). "Additionally, a phase 3 clinical research (NCT04724629) investigating the effectiveness and durability of treatment using IL-2 or an inhibitor of IL-17 has just been filed for patients with COVID-19." (PMID 36992283, 2023). "Furthermore, we observed that the COVID-19-specific IL2-AIS gene expression profile was observed across all disease severity groups and was particularly pronounced in a sub-group of community COVID-19 cases." (PMID 37700317, 2023). "Therefore, the increase in MBL and IL-2 expression in severe COVID-19 patients (C2S) can be interpreted as an attempt of the immune system to fight off the virus." (PMID 37949890, 2023). "In addition, this study established a relationship between the inflammatory response and the activation of coagulation, showing an increase in the percentages of IL1 β and IL2 in patients with COVID-19 who presented thrombotic events." (PMID 37112918, 2023). "In particular, PC1 reflected the known hyper-inflammatory phenotype of COVID-19 (with greatest contributions from IL-2, IL-6, IP-10, TNF-α, IL-10, IL-33 and IL-1β) which was independently associated with severe disease, requirement for invasive mechanical ventilation and mortality." (PMID 37063871, 2023). "Patients with severe COVID-19 have a high level of circulating IL-2, IL-6, IL-7, IL-10, and IFN-γ." (PMID 37654571, 2023). "Herein, as a proof-of-concept, we tested whether the modulation of the inflammatory response via IL-6 (colchicine), IL-17 (ixekizumab), and low doses of IL-2 could improve clinical outcomes of moderate to critical COVID-19 in hospitalized patients." (PMID 37075454, 2023). "Based on the results of the in vivo COVID-19 cytokine storm study, we focused on the IL-1β, IL-2, IL-6, TNFα, IL-4, and IL-10 molecular pathways as the key elements of the inflammatory response in order to identify the molecular mechanisms of peptidergic regulation of the cytokine storm in COVID-19." (PMID 37686182, 2023). "Ixekizumab and IL-2 have been demonstrated to be safe but ineffective for COVID-19 treatment." (PMID 37075454, 2023). "Furthermore, high serum levels of IL-17 and IL-2 and low levels of IL-4 appear to constitute a long-term profile of COVID-19 cytokines, and these markers are potential targets for long COVID-treatment and prevention strategies." (PMID 37237560, 2023). "The present study proposed that modulation of the inflammatory immune response via one of the following targets: IL-6, IL-17, and IL-2 could improve clinical outcomes of COVID-19 patients when compared to the SOC treatment." (PMID 37075454, 2023). "Contrarily, patients with COVID-19 who were severely infected experienced an excessive release of cytokines and chemokines, such as interleukin (IL)-1, IL-2, IL-6, IL-7, IL-8, IL-10, granulocyte-colony stimulating factor (GCSF), and tumour necrosis factor-alpha (TNF-α)." (PMID 36679947, 2023). "Additionally, INF-γ and IL-2 mRNA expression levels were similar between COVID-19 patients and vaccinated HCWs." (PMID 35529867, 2022).